Metazoa_SRP (Metazoan signal recognition particle RNA )
Gene: Miscellaneous RNA gene on chromosome 10 (100,666,695 to 100,667,009, reverse strand). Ensembl gene ENSG00000274660.
Gene Ontology:
Biological process: SRP-dependent cotranslational protein targeting to membrane, signal sequence recognition
Cellular component: signal recognition particle, endoplasmic reticulum targeting
Homologues: Orthologues: chimpanzee Metazoa_SRP (99% identical), macaque Metazoa_SRP (39% identical), macaque Metazoa_SRP (38% identical), macaque Metazoa_SRP (37% identical), macaque Metazoa_SRP (36% identical), macaque Metazoa_SRP (35% identical), macaque Metazoa_SRP (34% identical), macaque Metazoa_SRP (30% identical). Paralogues in human: RN7SL2 (54% identical), RN7SL296P (54% identical), Metazoa_SRP (53% identical), RN7SL1 (53% identical), RN7SL357P (53% identical), RN7SL14P (52% identical), RN7SL792P (52% identical), RN7SL145P (52% identical), RN7SL147P (52% identical), RN7SL19P (52% identical), RN7SL229P (52% identical), RN7SL3 (52% identical), and 690 more.
Diseases named in the same sentence as Metazoa_SRP in open-access papers:
Metazoa_SRP is named in the same sentence as 1 disease in open-access papers, as found by Europe PMC text mining. Sharing a sentence is not in itself a finding about the gene and the disease.
Metazoa_SRP shares sentences with these, for which no sentence is quoted: schizophrenia (1 paper).